ATXN7 (ataxin 7)
Diseases named in the same sentence as ATXN7 in open-access papers (continued):
Sharing a sentence is not in itself a finding about the gene and the disease.
Friedreich ataxia (8 papers, 2010 to 2026). An inherited condition that affects the nervous system and causes movement problems. "In European natives, pathogenic mutations should be searched in genes producing SCA1 (ATXN1), SCA2 (ATXN2), SCA3 (ATXN3), SCA6 (CACNA1A), SCA7 (ATXN7), SCA 12 (PPP2R2B), fragile X tremor ataxia syndrome (FMR1), SCA17 (TBP), CANVAS syndrome (RFC1), and Friedreich ataxia (FXN) [53﻿]." (PMID 35986227, 2023).
cone-rod dystrophy (7 papers, 2014 to 2025). Inherited retinal dystrophies that belong to the group of pigmentary retinopathies. "The causative mutation is an expanded CAG repeat in the ataxin-7 gene whose mutant protein product causes cerebellar and brainstem degeneration and retinal cone-rod dystrophy." (PMID 24759684, 2014). "Ataxin-7 interacts with CRX, a transcription factor regulating photoreceptor genes known to cause cone-rod dystrophy." (PMID 38976217, 2024). "Inappropriate interactions between expanded ataxin-7 and CRX are known to cause the phenotype similar to cone-rod dystrophy." (PMID 32973440, 2020). "In addition to causing cerebellar atrophy, polyglutamine-expanded ataxin-7 disrupts transcription of genes regulated by the cone-rod homeobox protein (CRX), resulting in a marked cone-rod dystrophy." (PMID 35422034, 2022). "Unlike SCA7, the mutations observed in ataxin-7 are not a polyglutamine expansion and our patient does not present with cone-rod dystrophy." (PMID 35422034, 2022). "In SCA7, expanded ATXN7 suppresses CRX transactivation, inducing cone-rod dystrophy in a transgenic mouse model." (PMID 41213927, 2025). "Studies in SCA7 mouse models and in vitro studies have demonstrated that polyglutamine expanded ataxin-7 disrupts the transcription of CRX, the cone-rod homeobox protein, in turn affecting the transcription of CRX-regulated genes resulting in a cone-rod dystrophy." (PMID 24759684, 2014).
Alzheimer disease (5 papers, 2011 to 2026). A progressive, neurodegenerative disease characterized by loss of function and death of nerve cells in several areas of the brain leading to loss of cognitive function such as memory and language. "First, we analysed if TDP-43, a PrLD-containing RBP shown to participate in SG formation and heavily implicated in other neurodegenerative diseases, such as amyotrophic lateral sclerosis (ALS) and Alzheimer’s disease (AD), was affected by mutant ATXN7." (PMID 35689166, 2022).
autosomal dominant cerebellar ataxia (5 papers, 2015 to 2024). A clinically and genetically heterogeneous group of neurodegenerative diseases characterized by a slowly progressive ataxia of gait, stance and limbs, dysarthria and/or oculomotor disorder, due to cerebellar degeneration in the absence of coexisting diseases. "The Ataxin7 (ATXN7) is one of autosomal dominant cerebellar ataxia (ADCA) which is a heterogeneous group of neurodegenerative disorders characterized by progressive degeneration of the cerebellum, brain stem and spinal cord." (PMID 27296891, 2016).
breast carcinoma (5 papers, 2011 to 2025). "ATXN7 was associated with several pathogenic traits, including type 2 diabetes, schizophrenia, breast cancer and cataracts, each associated with a unique variant (total n = 4)." (PMID 41254939, 2025). "ATXN7 was exclusively associated with pathogenic traits, including schizophrenia, diabetes, breast cancer, and cataracts." (PMID 41254939, 2025). "The detection of the Rad51C and ATXN7 fusion gene in the MCF-7 breast cancer cell line is intriguing." (PMID 27296891, 2016). "Next generation sequencing data have previously shown a fusion gene formed between Rad51C and ATXN7 genes in the MCF7 breast cancer cell line." (PMID 27296891, 2016). "Additionally, they include several non-neurological traits or diseases (such as ATXN1, atrial fibrillation; ATXN1/ATXN7, breast cancer; ATXN7, cataracts)." (PMID 41254939, 2025). "Further confirmation of its role in breast tumors was the discovery that the MCF-7 breast cancer cell line contains a RAD51C-ATXN7 fusion gene consisting of RAD51C exons 1–7 and ATXN7 exons 6–13." (PMID 21980511, 2011).
colorectal tumors (3 papers, 2016 to 2023). "We identified two forms of fusion mRNAs between Rad51C and ATXN7 in the colorectal tumors, including a Variant 1 (fusion transcript between Rad51C exons 1–7 and ATXN7 exons 6–13), and a Variant 2 (between Rad51C exons 1–6 and ATXN7 exons 6–13)." (PMID 27296891, 2016). "Here we report expression of the novel fusion gene between Rad51C and ATXN7 in human colorectal tumors, as well as association of the fusion gene with functional impairment of the FA DNA repair pathway." (PMID 27296891, 2016). "In conclusion we found a fusion gene between DNA repair gene Rad51C and neuro-cerebral ataxia Ataxin-7 gene in colorectal tumors." (PMID 27296891, 2016). "In conclusion a chromosomal translocation between DNA repair gene Rad51C and Ataxin-7 has been identified in colorectal tumors." (PMID 27296891, 2016). "In the current study we evaluated the frequency and expression of the fusion gene formed between Rad51C and ATXN7 in colorectal tumors and cell lines." (PMID 27296891, 2016).
depression (2 papers, 2022 to 2025). "For example, HTT, ATXN1, ATXN7, and CACNA1A were associated with neuropsychiatric disorders such as depression and schizophrenia." (PMID 41254939, 2025). "In one study, the lifetime odds of suffering from depression were significantly higher in people with >10 CAG trinucleotide repeats in ATXN7." (PMID 35401096, 2022). "Comparison of CAG repeat lengths between participants with and without diagnosed major depression showed the odds of depression nearly doubled with two relatively large ATXN7 alleles (i.e., in those with CAG repeat sizes above the median of 10)." (PMID 35401096, 2022).
diabetes (2 papers, 2024 to 2025). "For the rest of the genes with associations only in the cohort with diabetes (ZZEF1 and Chol, ATXN7, PC, HLA-DQA1 and HDL), this study is the first to identify an association and more research will be required to establish a comprehensive understanding of their impact." (PMID 39258111, 2024).
hereditary ataxia (2 papers, 2022 to 2026). An instance of an atactic disorder that is caused by an inherited genomic modification in an individual. "In patients with suspected hereditary ataxia, we identified expansions in loci that had not been assessed as part of routine diagnostic workup within the NHS at the time of recruitment, including ATN1, ATXN2, ATXN3, ATXN7, CACNA1A, FXN, TBP, and HTT." (PMID 35182509, 2022).
neuroblastoma (2 papers, 2017 to 2019). Neuroblastoma (NB) is the most common solid, extracranial childhood tumor. "Mirt-1cN also achieved ∼60% silencing of ataxin 7 in the SH-SY5Y human neuroblastoma cell line 48 h post-transfection (P < 0.0005), comparable with an ataxin 7-targeting shRNA (shR-1)." (PMID 28575281, 2017). "Finally, in a mouse neuroblastoma cell line and a SCA7 mouse model, it has been found that miR-124 mediates the interaction of lnc-SCA7 and Atxn7 transcripts." (PMID 30607747, 2019). "Two artificial mirtrons designed to target ataxin 7 silenced the endogenous ataxin 7 transcript in a patient-derived cell line, suppressed a downstream transcriptional target in a human neuroblastoma cell line and reduced aggregation of the mutant protein in transfected cells." (PMID 28575281, 2017).
retinal disease (2 papers, 2014 to 2024). "With the levels of silencing of mutant ataxin-7 (∼50%) in the retina that we observe with miS4, we predict improved retinal function in other SCA7 models with quantifiable retinal disease." (PMID 24759684, 2014).
sarcoma (2 papers, 2016 to 2025). A usually aggressive malignant neoplasm of the soft tissue or bone. "Also, in SCA7 models, the RBPs TDP-43, Muscleblind-like splicing regulator 1 (MBNL1), and fused in sarcoma (FUS) are recruited to expanded ATXN7 aggregates." (PMID 41213927, 2025). "Next, we investigated whether in vivo ATXN7 accumulation in the nucleus affected two RNA binding proteins: the transactive response DNA binding protein 43-kDa (TDP-43) and the Fused in sarcoma (FUS/TLS)." (PMID 27465358, 2016).
Blindness (1 paper, 2022). Blindness is the condition of lacking visual perception defined as a profound reduction in visual perception. "Although ATXN7 is expressed widely, the best characterized symptoms of SCA7 are remarkably tissue specific, including blindness and degeneration of the brain and spinal cord." (PMID 35401096, 2022).
Gait ataxia (1 paper, 2014). A type of ataxia characterized by the impairment of the ability to coordinate the movements required for normal walking. "In transgenic mice, expression of the Q92 ataxin-7 in all CNS neurons, except for Purkinje cells, led to severe Purkinje cell degeneration, development of gait ataxia, and formation of truncated ataxin-7 nuclear aggregates that correlated with disease phenotype onset and even to premature death." (PMID 26331028, 2014).
invasive breast carcinoma (1 paper, 2016). A carcinoma that infiltrates the breast parenchyma. "We have also shown for the first time that seven of the known invasive breast cancer predisposition loci not previously shown to be associated with DCIS have comparable ORs for IDC and DCIS: rs4973768 (SLC4A7), rs3821902 (ATXN7), rs10995190 (ZNF365), rs554219 (CCND1), rs3757318 and rs2046210 (ESR1)." (PMID 26884359, 2016).
medulloblastoma (1 paper, 2011). A malignant, invasive embryonal neoplasm arising from the cerebellum. "ATXN7 is highly expressed in medulloblastoma tumors and cell lines." (PMID 22016811, 2011).
non-small cell lung carcinoma (1 paper, 2022). A group of at least three distinct histological types of lung cancer, including non-small cell squamous cell carcinoma, adenocarcinoma, and large cell carcinoma. "Silencing ATXN7 circRNAs in non-small cell lung cancer cells in vitro decreased their proliferative and invasive abilities." (PMID 35401096, 2022). "An analysis of 57 non-small cell lung cancer cell tissue samples found that 45 (79%) had increased ATXN7 circRNA levels." (PMID 35401096, 2022).
type 2 diabetes (1 paper, 2025). "Additionally, metabolic traits such as type 1 and type 2 diabetes were linked to ATXN2 and ATXN7, which is in line with the fact that metabolic dysfunction is observed in several polyQ disorders." (PMID 41254939, 2025).
neurodegenerative disease (26 papers, 2013 to 2026). A disorder of the central nervous system characterized by gradual and progressive loss of neural tissue and neurologic function. "Other polyQ-containing proteins such as ATXN7 and huntingtin are associated with the development of neurodegenerative diseases when their N-terminal polyQ domains are expanded." (PMID 38128014, 2023). "Spinocerebellar Ataxia Type 7 (SCA7) is a rare inherited neurodegenerative disease caused by polyglutamine repeat expansion in Ataxin 7 (ATXN7), a product of the SCA7 gene." (PMID 33339180, 2020). "Several subunits of the SAGA and ATXN7 also involved in pathogenesis of neurodegenerative diseases and Gcn5 deletion accelerates its progression." (PMID 32134955, 2020). "As with many neurodegenerative disease proteins, ataxin-7 is ubiquitously expressed in the brain and yet the disease manifests in specific brain regions." (PMID 24160175, 2013). "The progressive retinal and neurodegenerative disease Spinocerebellar Ataxia type 7 (SCA7) is caused by CAG trinucleotide repeat expansion of the ATXN7 gene, resulting in polyglutamine (polyQ) expansion at the amino terminus of the Atxn7 protein." (PMID 31348003, 2019). "Atxn7, a subunit of SAGA chromatin remodeling complex, is subject to polyglutamine expansion at the amino terminus, causing spinocerebellar ataxia type 7 (SCA7), a progressive retinal and neurodegenerative disease." (PMID 31348003, 2019). "This study implicates HDAC3 and ataxin-7 interaction as a target for therapeutic intervention in SCA7, adding to a growing list of neurodegenerative diseases that may be treated by HDAC inhibitors." (PMID 24160175, 2013).
infection (8 papers, 2016 to 2023). The state of being infected such as from the introduction of a foreign agent such as serum, vaccine, antigenic substance or organism. "FUS/TLS and ATXN7 co-localized in ~70 % of intranuclear inclusions at 12 weeks post-infection." (PMID 27465358, 2016).
retinopathy (5 papers, 2016 to 2024). "Research on mechanisms of the retinal disorder in SCA7 showed that overexpression of human ataxin-7 provokes ERG abnormalities and outer retinal degeneration." (PMID 38976217, 2024). "PolyQ expanded ataxin-7 elicits neurodegeneration in cerebellar Purkinje cells, however, its impact on the SCA7-associated retinopathy remains to be addressed." (PMID 36675972, 2022).
cancer (2 papers, 2017 to 2023). A tumor composed of atypical neoplastic, often pleomorphic cells that invade other tissues. "These genes include well annotated tumor-suppressor genes and oncogenes (e.g., TGFBR2 and MYC as well as genes that have never been previously linked to cancer in general, or to increased BC risk (including ADCY3, ATXN7, CFL1 and LPAR2)." (PMID 36991492, 2023).
tumor (1 paper, 2023). "For example, ATXN7 scored as a strong tumor-suppressor using CRISPRko in 2D and 3D assays but did not score with CRISPRi." (PMID 36991492, 2023).
ATXN7 also shares sentences with these, for which no sentence is quoted: dentatorubral-pallidoluysian atrophy (35 papers); spinobulbar muscular atrophy (10); cerebellar ataxia (9); spinocerebellar ataxia type 1 (6); amyotrophic lateral sclerosis (5); neurological disorder (5); Parkinson disease (4); cerebellar degeneration (3); Huntington disease-like 2 (3); Cerebellar atrophy (2); fragile X-associated tremor/ataxia syndrome (2); frontotemporal dementia (2); myotonic dystrophy type 1 (2); schizophrenia (2); spinocerebellar ataxia type 2 (2); Adult onset (1); airway hyperresponsiveness (1); Anxiety (1); asthma (1); ataxia telangiectasia (1); atrial fibrillation (1); Atrophy (1); autosomal dominant polycystic kidney disease (1); Brainstem atrophy (1); breast tumors (1); cataract (1); Cognitive impairment (1); coloboma (1); colon cancer (1); colorectal cancer (1).
A further 48 diseases each share a sentence with ATXN7 in 1 paper.